CD44 (CD44 molecule (IN blood group))
Diseases named in the same sentence as CD44 in open-access papers (continued):
Sharing a sentence is not in itself a finding about the gene and the disease.
tumor (continued). "Thus, further research is necessary to investigate whether the CD44+CD104low subpopulation of the M13HS-2 and -8 tumor hybrids exhibit prospective CSC properties." (PMID 38139138, 2023). "Triple-positive CD44/CD117/CD133 cells showed downregulated ALDH expression, which sheds light on the hypothesis that CSCs are more heterogeneous than expected and may show less differentiated levels of tumor in the trunk region." (PMID 36982993, 2023). "CD44 is a single-span transmembrane glycoprotein involved not only in mediating both cell-cell and cell-matrix interactions but is also a key player in transmitting HA signaling in tumor progression." (PMID 37568628, 2023). "CSCs in these tumours were somewhat different, the markers of which were PLP, Nestin, P75, GAP43, and Sox10, with GFAP, S100, and GAP43 (as a Schwann cell marker) in differentiated cells, in neurofibroma and MPNST; and Oct4, SOX2, Nanog, MYC, KLF4, CD133, CD44, and CXCR4 in CSCs of schwannoma." (PMID 37370764, 2023). "Moreover, scRNA-seq analysis revealed that fibroblast and ductal cells might affect malignant tumor cells via MIF-(CD74+CD44) and SPP1-CD44 axis." (PMID 38095640, 2023). "Further analysis of tumor-infiltrating CD8+ T cells revealed a less exhausted phenotype, with a significant reduction in the fraction of Tim3+, LAG3+, Blimp1+, and EOMES+ as well as annexin V+ CD8+ T cells, but with a modest increase in T-bet+ cells (P = 0.1878) and CD44+CD8+ T cells." (PMID 38038129, 2023). "AMBL was found to express ABCG2, ALDH1, BMI1, CD133, CD166, CD44, and c-Myc in peripheral and/or central cells of the parenchyma at variable extent and intensity levels, as well as CD34 in spindle-shaped stomal cells and LGR5 and NANOG in both epithelial and stromal tumor components." (PMID 37761874, 2023). "CD44 is also a prominent activation marker that distinguishes memory and effector T cells from their naïve counterparts; thus, we hypothesized that TAM-SPP1+ could also facilitate tumor cell evasion by suppressing CD8+ T cell activation." (PMID 37336873, 2023). "Moreover, the popliteal lymph node of tumor-bearing mouse at 1 h after intra-footpad injection of DXBTZ-CB /CSA displays in greenish blue color, suggesting that the nanoagent can track the metastatic cancer cells in lymphatic system via CD44 targeting." (PMID 37400468, 2023). "In addition to soluble MMPs, CD44 can form a protein complex with the membrane bound MMP14 (aka MT1-MMP) at the cell surface, thereby directing it to the leading edge of migrating cells and promoting tumor cell invasion." (PMID 36876041, 2023). "Indeed, in the presence of free HA, internalization of the nanoparticles into tumor cells was significantly reduced and comparable to that obtained using a CD44-negative tumor." (PMID 37287910, 2023). "In conclusion, CD44 may interact with SPP1, and SLC9A1 to promote certain tumor progression." (PMID 37316699, 2023). "CD44 expression in the tumor periphery also correlated with HI-type GBM, but both specificity and sensitivity in differentiating HI-type tumors from LI-type tumors were much greater with evaluation by P/C ratio of CD44 expression than by CD44 expression in the tumor periphery alone." (PMID 37760811, 2023). "While these data suggest that CD44 is a key determinant of the phenotypic heterogeneity observed within tumours, it does not appear to reliably identify CSC populations in established cell lines, thus raising questions about the suitability of cell lines for the screening of CSC-specific therapies." (PMID 37958796, 2023). "Besides, subsequent exploration suggested that TRIM9 shRNA treatment resulted in increased mRNA and protein expression of stem-like phenotypic biomarkers on tumor cells, including CD133 and CD44, whereas TRIM9 overexpression demonstrated completely opposite effects." (PMID 37124931, 2023). "In contrast, single tumor cells that do not express CD44 die within 48–72 h of detachment." (PMID 37492150, 2023).
tumor (continued). "Interestingly, it has been reported that the HS site in CD44 v3 exon is involved in metastatic tumour progression but does not affect cell proliferation." (PMID 36528833, 2023). "Most LSCC tumor cells did not express ALDH1 (94.5%) but did express CD44 (75%)." (PMID 38126564, 2023). "This approach revealed concomitant expression of CD44 and SREBP2 in a subset of cells of the invasive area of the tumor, suggesting that the metastatic progression might require the acquisition of both metabolic and phenotypic features by the cells of the primary tumors." (PMID 36732018, 2023). "Osteopontin/CD44 could control CD8+ T cell activation and tumor immune evasion." (PMID 36776876, 2023). "Moreover, CD44v8–10, but not CD44s, rescued the tumor-initiating potential of the CD44-depleted gastric cells." (PMID 37005380, 2023). "Although obtained by the same methods used for MTS, tumor spheres (MTDS), being a single-cell suspension of tumor tissue, are characterized by the abundance of many cancer stem cells (CSCs), which can be highlighted by analyzing the expression of specific markers such as CD133, CD44, and ALDH." (PMID 37894363, 2023). "CD44-ICD is an intracellular free fragment that translocates to the nucleus and activates the transcription factors of various genes, resulting in enhanced tumor proliferation, glycolytic metabolism, and increased stemness in tumors (particularly as cancer stem cells)." (PMID 37835592, 2023). "In-depth analysis of β4+ tumor cells’ phenotypic characteristics taking into consideration stemness and EMT features revealed a significantly increased proportion of E-cadherin+ and CD44+CD24- cells in patients with liver metastases compared to patients with lung or without distant metastases." (PMID 36769251, 2023). "However, FSTL1+ tumor cells, which were most abundant in the PD-1+SMI group, expressed high levels of the lung CSCs marker genes CD44 and ALCAM, and the CSCs score was significantly higher than those in the other subclusters, except for NEAT1+ and XIST+ tumor cells." (PMID 37430270, 2023). "Notably, the observed reductions in CD44+ CSCs induced by doxycycline were independent of histological grade, tumor diameter (small, large), and molecular subtype." (PMID 37511298, 2023). "Finally, the results suggested that CD44 may interfere with the TME by influencing the expression of immune-related genes and immune checkpoint genes, which mediates tumor progression and metastasis." (PMID 37117249, 2023). "Moreover, CD44 is widely used, alone or in combination, with other SC markers, to isolate or enrich CSCs using fluorescence-activated-cell-sorting (FACS) of cells from patient tissues, xenograft tumor tissues, or tumor cell cultures." (PMID 37005380, 2023). "For instance, the expression level of CD44, which may interact with Eno1 and MSN, can be expressed higher in cancer cells than noncancer cells, and thus the impact of CD44-mediated cytotoxicity is stronger in tumor cells." (PMID 36810561, 2023). "As CD73 is overexpressed in tumor-initiating cells (TIC) to promote stemness, and that TIC rely on OXPHOS to support tumorigenesis, we next evaluated the impact of CD73 on the metabolic fitness of putative TIC (ALDHHigh CD44+ CD24-) derived from MDA-MB-231 cell cultures." (PMID 37261423, 2023). "Furthermore, CD44 could specifically interact with the PEX sequence of MMP14, activate MMP2, and regulate cell migration, suggesting that CD44 and MMP2 may be closely related to the tumor metastasis." (PMID 36192574, 2023). "The results confirmed in vivo the significant reduction of xenograft tumor volume and weight in mice treated with casticin only, or agomir-148a-3p only, the reduction of DNMT1 activity and mRNA levels, and the reduction of the stemness biomarker CD44 expression." (PMID 37304067, 2023).
tumor (continued). "As in NSCLC, PKM2KO T cells exhibited a central memory-like phenotype, with elevated CD44 + CD62L + proportions at both timepoints in both tissues and enhanced TCF1 and Eomes expression at the later timepoint, marginally in the draining lymph node and significantly in the tumor." (PMID 37790365, 2023). "Furthermore, a protein–protein interaction analysis obtained from the STRING website showed a direct interaction between SPP1 and CD44, MMP3, MMP7, TIMP1 and fibronectin-1, all of which are directly involved in the extracellular matrix remodeling and promotion of tumor metastasis." (PMID 38067407, 2023). "Notably, under Y15 treatment, CM from ID1OE M1-like macrophages no longer enhanced tumor cell invasiveness, tumor sphere-forming ability, or CD44 protein abundance." (PMID 37996458, 2023). "Additionally, uBCOs exhibited the expression of designated tumor stem-cell markers, in detail, CD24 and CD44, further highlighting their potential for studying BC stem cells and their capacity to expansion, as well as their responses to systemic anti-cancer agents in BC." (PMID 37681920, 2023). "Correlation analysis of the alternative splicing events of CD44 with expression levels of CELF1 and ELAVL1 based on RNA-Seq data from TCGA revealed that high expression of CELF1 and/or ELAVL1 is correlated with the inclusion of CD44 variable exons in eight tumor types." (PMID 38106992, 2023). "There was an increase in number of CD4+ and CD8+ TEF cells and an increase in the fraction activated CD44+CD8+ T cells in dLN, a systemic increase of CD4+ and CD8+ TEF and TCM-like cells and enhanced T cell activation in the spleen of Shp2f/fLysMCre compared to Shp2f/f MC17-51 tumor-bearing mice." (PMID 36581713, 2023). "In addition, the P/C ratio of CD44 expression showed much higher sensitivity and specificity for predicting invasiveness of GBM (100% and 83.3%, respectively) than CD44 expression in the tumor periphery (85.7% and 79.2%, respectively)." (PMID 37760811, 2023). "However, as a small part of the tumor population, gastric CSCs are not used to investigate the optical imaging and in vivo distribution of CD44/CD133-ATRA-PLPN." (PMID 36182897, 2022). "However, CD44 was upregulated and MAL was significantly downregulated in tumor tissues." (PMID 35093120, 2022). "In vivo tumor studies showed that KO of STC1 led to a drastically reduced tumor growth rate, significantly downregulated CSC markers (CD44 and CD166) on the surface of tumor cells, and reduced CD44+/CD166+ CSC-like cell populations within the general A549 tumor cell population." (PMID 36499099, 2022). "Their multiplication resulted in a heterogeneous population of cells composed of the CD44+CD24−/Lineage− population as well as non-tumorigenic cells that could compose the bulk of the tumour mass." (PMID 35159385, 2022). "To determine whether the protective effects of IP6 are mediated via the effect on the expansion of the TICs/CSCs pool, we analyzed the TICs pool (for dual expression of CD44 and BMI-1) as a function of tumor aggressiveness (with or without IP6 treatment)." (PMID 36077751, 2022). "CD44 is a nonkinase family and single-transmembrane glycoprotein that is expressed at different levels on the cell membranes of embryonic stem cells, bone marrow cells, tumor cells, etc.." (PMID 35936713, 2022). "Also, reduced CD44 and CD31 expressions were observed in CCL8 antibody-treated tumors, suggesting that the blocking of CCL8 reduced the THP-1-derived M2-like macrophages-induced increase of tumor onset and angiogenesis." (PMID 35680853, 2022). "As a transmembrane receptor for hyaluronic acid (HA) and a co-receptor for many growth factors and cytokines, CD44 is widely overexpressed in a vast array of tumor cells, including cancer stem cells, and is a critical regulator for cell-matrix adhesion, cell growth, EMT, and tumor progression." (PMID 35707369, 2022).
tumor (continued). "Since the proliferative and tumor stemness phenotypes were significantly affected by FAM64A inhibition, we next detected markers reflecting proliferation and cancer stemness, and found that the levels of PCNA, CD44, SOX2, and BMI-1 were all markedly decreased upon reduction of FAM64A." (PMID 35538067, 2022). "created a non-immunomodulating bsApt that targeted CD44 and EpCAM, two tumor cell surface markers that are overexpressed in ovarian cancer and are associated with malignant ascites, chemoresistance, decreased survival, and epithelial-to-mesenchymal transition (EMT)." (PMID 35141049, 2022). "The proportion of DN T cells co-expressing CD44 and CD69 (“DN TRM-like”) in captopril-treated regenerating liver tissue significantly increased, and this corresponded with an increase in PD-1 expression on DN TRM-like cells in captopril-treated regenerating liver and tumour." (PMID 35563674, 2022). "Immune phenotypic analysis of tumor-infiltrating T cells revealed that co-administration of CXB to the combination of CTX and ICB boosted the activation of CD8+ and CD4+ T cells, which displayed significantly higher production of IFNγ and surface expression of the activation marker CD44." (PMID 35440553, 2022). "As CCA cells use EVs to interact with surrounding mesenchymal stem cells to modulate the microenvironment and enhance the tumor growth, it can be postulated that the reduction of these cell interactions via CD24 and CD44 loaded EVs after SIRT may reduce tumor growth and progression." (PMID 35954154, 2022). "The results showed that Lipo-CD44-TF could deliver triple fusion specifically to the tumor but not completely inhibit its growth." (PMID 35456655, 2022). "Moreover, HA-based surface modification may give Bio-MOF targeted anti-cancer characteristics including the promotion of aggregation on tumor sites and increased MOF uptake by CD44-positive cancer cells." (PMID 36419626, 2022). "The bioluminescence (BLI) signals showed that Lipo-CD44-TF could specifically target the tumor by recognizing the CD44 antigen, while Lipo-TF/GCV does not target cancer cells." (PMID 35456655, 2022). "Furthermore, two other mechanisms by which MT1-MMP augments tumor progression are the shedding of the adhesion molecule CD44 and the cleavage of MHC-1 chain-related molecule A from the tumor cell surface, which makes them resistant to killing by NK (Natural Killer) cells." (PMID 36289525, 2022). "Therefore, we sought to detect the expression of SOX2, CD44, and ALDH1A1 in CxSCC tumor buds." (PMID 35860042, 2022). "However, a pertinent issue related with the utilization of CD44 and CD133 lies in selective removal of a subset of CSCs only and may promote phenotypic shift and differentiation in tumor unintentionally." (PMID 35456698, 2022). "We investigated whether the T-cell populations observed in regenerating liver and tumour tissue had features of TRM, defined by the expression of murine hepatic TRM markers, CD44 and CD69 (termed “TRM-like cells”), and assessed the effect of captopril on these populations and their PD-1 expression." (PMID 35563674, 2022). "CD44 expression was quantified in ex vivo irradiated or non-irradiated tumour slices, obtained from biopsy of patients prior to treatment, in order to investigate whether irradiation could improve the predictive value of this CSC marker." (PMID 35055060, 2022). "Our results show that PFKFB3-mediated targeting by PFK158 or genetic manipulation resulted in inhibition of glycolysis and of tumor progression, resulting in diminished cancer “stemness” by decreasing both surface and intracellular stem cell marker expressions such as CD133, CD44, Aldh1, and Sox2." (PMID 35804016, 2022). "Additionally, PBA-Niclo-SLNs significantly inhibited STAT3, TNBC stem cell populations (CD44+/CD24−), and EMT (epithelial–mesenchymal transition) markers along with increased tumor-site accumulation with significant tumor regression and enhanced survivability of TNBC-bearing mice." (PMID 36077466, 2022).
tumor (continued). "In addition, even high-dose BCNU would not be able to control the tumor cells of highly invasive type GBM expressing high CD44." (PMID 35624954, 2022). "The results showed that not every tumor tissue expressed CD44, CD24 or ABCG2, but the expression of EpCAM could be detected." (PMID 36132125, 2022). "In addition, some scholars have found that CD24+/CD44+- EPCAM+ cell subsets have specific gene expression profiles, and these stemness-related cell subclones in HCC enable tumor cells to acquire great genetic richness, leading to the failure of HCC targeted therapy." (PMID 36303541, 2022). "However, all CD44-expressing tumor cells are likely not CSCs nor do all CD44-expressing cells possess an EMT phenotype." (PMID 35931675, 2022). "Analysis of the proportion of CD4+ T, CD8+ T, and central memory T cells (CD44+ CD62L+) showed that SPNI-mediated photodynamic immunotherapy can be used as a vaccine for cancer to stimulate strong anti-tumor T cell immunity, which helps to inhibit local and surrounding tumor growth." (PMID 35832074, 2022). "In addition, CD44 depletion impairs certain gene signatures, such as those for platelet-derived growth factor (PDGF) isoforms and PDGF receptors, as well as signatures related to hypoxia, glycolysis, and anti-tumor immune responses." (PMID 35954411, 2022). "However, no prolonged survival of tumor-bearing mice harboring CD44 deletion in myeloid cells was observed." (PMID 35992852, 2022). "In contrast, one study reported that tumor size did not alter the CD44 expression pattern." (PMID 35200757, 2022). "The results showed that trifunctionalized HA increased the morphological stability of GNRs-HA-FA-DOX, increased tumor targeting, and prolonged in vivo circulation time, where the addition of FA further promoted the endocytosis of GNRs and DOX by MCF-7 cells compared to the CD44 targeting of HA." (PMID 36091467, 2022). "The newest research indicated that CD44 played important roles that could stabilize SLC7A11 by increasing the recruitment of OTUB1 and promotes the interaction of SLC7A11 with OTUB1, thereby inhibiting the ferroptosis in tumor cells." (PMID 33869286, 2021). "In addition, treating this mixture of immune cells with the immune checkpoint inhibitors (anti-CTLA4 and anti-PD1), which allow for downregulation of Tregs, proper activation of CTL, Th, and memory T cells, with subsequent suppression of tumor cells through downregulation of CD133, CD34, and CD44." (PMID 37305162, 2021). "The CD44 + CD24 + ESA + phenotype exhibited a 100-fold increase in tumor-initiating capacity versus non-tumorigenic cancer cells, gauged from a very little number of sorted cells required to produce tumors histologically similar to primary PC in immunocompromised mice." (PMID 34453639, 2021). "Due to the detection of cancer stem cells via the expression of biomarkers, tumour initiating cells have been identified in leukemia (CD34+, CD38−) and in solid tumours including glioma (CD133+, ALDH1+), breast (EpCAM+/CD44high/CD24low, ALDH1+), and head and neck squamous carcinoma (CD44+)." (PMID 34680897, 2021). "In both MYCN amplified and non-amplified neuroblastoma, CD44 was found to play a dual role that is when un-methylated was manifesting high expression levels, redirecting to tumor suppression, while when hyper-methylated it was related to tumor progression." (PMID 34842635, 2021). "Since tumor cells can regulate recognition signals and functionally modulate the expression of ligands for receptors on NK cells to mediate NK cell activity, we further investigated the dissimilarity in the expression of HLA-E and MICA/B in TNBC, RT-R-TNBC, and CD24−/low/CD44+ cells." (PMID 34502547, 2021). "The anti-tumoral effect was correlated with the generation of CD4+, CD8+ T cells, and CD44+ CD62L- CCR7low CD127low T-effector memory cells, and the reduction of CD4+ CD25+FoxP3+ Tregs, Arg1+ CD11b+ Gr1+, and Arg1+ and CD11b+ Ly6+ myeloid-derived suppressor cell populations within the tumor." (PMID 34957134, 2021).